MDM2 (MDM2 proto-oncogene)
Diseases named in the same sentence as MDM2 in open-access papers (continued):
Sharing a sentence is not in itself a finding about the gene and the disease.
breast carcinoma (continued). "The presence of high levels of MDM2 and MDMx in many breast cancers suggests that these data should be considered in the treatment of breast cancer." (PMID 24667108, 2014). "Overexpression of MDM2 is observed both in epithelial cells of transgenic mice with induced mammary carcinomas and in various human tumors, including breast cancer." (PMID 25326024, 2014). "Amplification of Mdm2 was identified only in two of these samples (1.7%) indicating that Mdm2 amplification is uncommon in primary breast cancers." (PMID 24667108, 2014). "The aim of this study was to ascertain the effects of MDM2 expression on the invasive potential of breast cancer cell lines in vitro, in addition to the effects of MMP9 expression." (PMID 24236052, 2013). "In the estrogen receptor positive (ER+) mdm2 G/G SNP309 breast cancer cell line, T47D, we observed an increase in endogenous MDM2-C protein with estrogen treatment." (PMID 24147044, 2013). "In vitro studies have confirmed that the overexpression of MDM2 confers a more aggressive phenotype to breast cancer cell lines, including higher levels of cell motility and invasion, in addition to inducing the expression and activity of MMP9." (PMID 24236052, 2013). "We conclude that MDM2 plays an important role in the invasion and metastasis of breast carcinoma via the degradation of the surrounding extracellular matrix." (PMID 24236052, 2013). "Amplification was observed over cancer genes previously implicated in breast cancer development including ERBB2, CCND1, MYC, MDM2, ZNF217, and ZNF703 and a homozygous deletion involving MAP2K4 was identified." (PMID 22608084, 2012). "In summary, 25-OCH3-PPD is a potential therapeutic and anti-metastatic agent for human breast cancer through down-regulating MDM2." (PMID 22911819, 2012). "MDM2-rs2279744, also referred to as MDM2 SNP309, was originally described as a potential functional SNP biomarker for predisposition to breast cancer." (PMID 23145162, 2012). "In the present study, after demonstration of its anti-breast cancer activity in vivo, we attempted to explore the molecular mechanisms for the effects of 25-OCH3-PPD on both primary and metastatic breast cancers, showing MDM2 to be a major target." (PMID 22911819, 2012).
breast carcinoma (continued). "In summary, our preclinical data indicate that 25-OCH3-PPD, a novel MDM2 inhibitor, is a potential therapeutic and anti-metastatic agent for human breast cancer." (PMID 22911819, 2012). "It would be interesting to determine if knockdown of Mdm2 would induce senescence of SCP subtype breast cancers." (PMID 21223569, 2011). "In this study, we adopted a hospital-based case-control study to investigate the association between MDM2 SNP309 and onset of breast cancer in the female Taiwanese population." (PMID 19144119, 2009). "For the first time, this study explores the effect of the MDM2 SNP309 genotype on Taiwanese breast cancer patients." (PMID 19144119, 2009). "A larger sample size is expected to assess the association between MDM2 SNP309 and breast cancer incidence in Taiwanese women in the future." (PMID 19144119, 2009). "Our data demonstrate that patients with BRCA1/2 breast cancers harboring any of the three MDM2 SNP309 had similar cancer onset ages." (PMID 19226467, 2009). "Disease onset age of breast cancer did seem to vary according to MDM2 309SNP genotype in the BRCA1/2 groups." (PMID 19226467, 2009). "Taken together, increased sample size and investigation of other genetic factors will be important in better understanding the effects of MDM2 SNP309 on breast cancer development in the Taiwanese population." (PMID 19144119, 2009). "DNA from breast cancer patients was obtained for analysis of one of the three common BRCA1/2 mutations and MDM2 SNP309." (PMID 19226467, 2009). "Nevertheless, smaller sample size has also been reported in findings on the effects of MDM2 SNP309 on breast cancer and endometrial cancers." (PMID 19144119, 2009).
breast carcinoma (continued). "MDM2 SN309 was further reported to accelerate sporadic breast cancer formation in Caucasians women in a gender-specific and hormone-dependent manner." (PMID 19144119, 2009). "Our data suggested that the homozygous MDM2 SNP309GG genotype simultaneously affected the risk and the onset age of breast cancer in the Taiwanese population." (PMID 19144119, 2009). "Among the breast cancer patients, the mean ages at diagnosis for the TT, TG and GG genotypes of MDM2 SNP309 were 53 (range 42–66), 51.5 (range 21–72) and 46.9 (range 30–64) years old, respectively." (PMID 19144119, 2009). "In the breast cancer cohort MDM2 SNP309 was also analysed with respect to age at cancer diagnosis and pathological variables." (PMID 18828900, 2008). "Intron 1 of MDM2 was PCR amplified and directly sequenced from 299 breast cancer patients and 275 cancer free controls and compared with clinical and pathological parameters." (PMID 18828900, 2008). "Upon sequencing MDM2 intron 1 three additional SNPs were detected in the control and breast cancer populations; 344T>A; 285G>C and 443G>T, the latter two representing previously unreported polymorphisms." (PMID 18828900, 2008). "This study examined clinical associations of breast cancer with SNP309 in a Scottish Caucasian population and investigated additional MDM2 intron 1 polymorphisms." (PMID 18828900, 2008). "Overexpression of MDM2 is observed both in epithelial cells of transgenic mice with induced mammary carcinomas and in multiple human tumors, including breast cancer." (PMID 17537232, 2007). "Overexpression of MDM2 has however been found in up to 73% of breast cancers and breast cancers comprised 17 out of 66 of the tumours reported by Bond's cohort of Li Fraumeni individuals." (PMID 16563154, 2006). "In a patient cohort with stage IV cancer patients, all six patients (bladder cancer, breast cancer, endometrial stromal sarcoma, lung adenocarcinoma, squamous cell carcinoma of the hypopharynx) with MDM2 amplification showed a time-to-treatment failure of under two months." (PMID 41299419, 2025). "We aim to expand on our prior work and analyze the GATA3mut mutational landscape based on ctDNA next generation sequencing (NGS), and furthermore, we analyze GATA3mut proteomic data to understand the mechanism behind the efficacy of MDM2 inhibition in GATA3mut HR +/HER2− breast cancer." (PMID 40439821, 2025). "Similarly, glioblastoma with high MDM2 levels exhibits greater resistance to therapy and reduced survival outcomes, while breast cancer frequently displays elevated MDM2 expression, correlating with poor clinical progression." (PMID 41170373, 2025).
breast carcinoma (continued). "We also aimed to elucidate the regulatory function of MDM2 in breast cancer." (PMID 40191734, 2025). "Although MDM2 gene amplification has been reported in luminal breast cancers, the role of epitranscriptomic mechanisms in MDM2 regulation remains largely unexplored in breast cancers." (PMID 40381037, 2025). "We investigated the potential associations between genotypes of MDM2 SNP309 (rs2279744), SNP285 (rs117039649) and del1518 (rs3730485) and neutrophil counts in breast cancer patients receiving neoadjuvant sequential epirubicin and docetaxel, with additional G-CSF, in the DDP-trial (NCT00496795)." (PMID 39979836, 2025). "The effect of MA242 on MDM2 expression was assessed in breast cancer cell lines." (PMID 40046748, 2025). "Therefore, targeting MDM2 represents a promising strategy for developing more effective therapy for breast cancer, particularly TNBC." (PMID 40046748, 2025). "Notably, MDM2 expression exhibits a positive correlation with ERα expression in human breast tumors and ERα-positive breast cancer cell lines." (PMID 40580306, 2025). "Hence, the natural terpenoid compound, 27-deoxyactein, holds promise as a strong candidate for inhibiting MDM2, warranting further investigation as a lead compound in experimental and clinical studies to enhance breast cancer treatment efforts." (PMID 40308267, 2025). "Finally, this study provides a comprehensive overview of the role of MDM2 in breast cancer and the significance of therapeutic targeting of MDM2." (PMID 40191734, 2025). "First, we determined MDM2 levels in breast cancers using GTEx normal breast tissue (n = 179), TCGA normal breast tissue (n = 113), and TCGA breast cancer tumor subtypes (luminal A (n = 562), luminal B (n = 214), basal (n = 190), HER2-enriched (n = 81), and normal-like (n = 39)." (PMID 40381037, 2025). "The overexpression of MDM2 is detected in many ER + breast cancers, indicating that MDM2 is an essential ER + oncogene which may be targeted for cancer treatment." (PMID 40580306, 2025). "Hepatitis B virus X-interacting protein (HBXIP) is a potent inducer of MDM2 in breast cancer cells." (PMID 40191734, 2025). "Interestingly, the overexpression of TSG101 led to a significant increase in MDM2 expression in established mammary tumors (right)." (PMID 40624726, 2025). "MDM2 influences tumor development and progression in breast cancer through multiple pathways." (PMID 38741108, 2024). "The addition of the SDF-1 chemokine to breast cancer cells upregulated MDM2 and MDM4." (PMID 39766093, 2024). "As such, we identified an SDF-1/CXCR4/MDM2/MDM4 signal transduction axis that we speculate participates in driving breast cancer metastasis." (PMID 39766093, 2024). "Therefore, PTEN will lead to the aggregation of MDM2 in the cytoplasm, and PTEN deletion will activate the MDM2-mediated anti-apoptosis process, resulting in abnormal proliferation of breast cancer cells." (PMID 38741108, 2024).
breast carcinoma (continued). "In breast cancer, approximately 38% of patients exhibit increased MDM2 protein expression." (PMID 36923534, 2023). "In human breast cancer, the MDM2 protein concentration was detected as a prognostic biomarker." (PMID 37185737, 2023). "The co-immunoprecipitation first demonstrated that S100A6 and MDM2 could interact with each other in breast cancer cells." (PMID 37217945, 2023). "Moreover, the S100A6-mediated MDM2 degradation suppressed the growth of breast cancer and enhanced sensitivity to paclitaxel both in vitro and in vivo." (PMID 37217945, 2023). "Moreover, MDM2 enhanced the invasion and migration of breast cancer cells by upregulating the expression of MMP-9." (PMID 37818185, 2023). "Furthermore, the S100A6-mediated MDM2 degradation suppressed the growth of breast cancer and enhanced its sensitivity to paclitaxel both in vitro and in vivo." (PMID 37217945, 2023). "In addition, research has concluded that the overexpression of the MDM2 gene is related to the augmentation of breast cancer." (PMID 37374977, 2023). "When focused on specific indications, MDM2 could be used with MCL1 inhibitors in breast cancer and lung adenocarcinoma." (PMID 35249548, 2022). "In order to evaluate the action of ZLM-7 on the expressions of 14-3-3 sigma and MDM2 in breast cancer, we firstly investigated the expressions of those genes in two independent human breast cancer cell lines, MDA-MB-231 and MCF-7, as well as in the normal MCF-10A mammary epithelial cell line." (PMID 35890172, 2022). "Collectively, ZLM-7 could inhibit MDM2 via upregulating 14-3-3 sigma expression, thereby blocking the breast cancer progression." (PMID 35890172, 2022). "The present study suggests that the treatment of ZLM-7 could block cell-cycle progression and induce cell-cycle arrest of breast cancer both in vitro and in vivo via regulating 14-3-3 sigma/MDM2 axis." (PMID 35890172, 2022).